CD4 (CD4 molecule)
Diseases named in the same sentence as CD4 in open-access papers (continued):
Sharing a sentence is not in itself a finding about the gene and the disease.
infection (continued). "TRIM5α restriction provides a potent block to HIV-1 infection of rhesus macaque CD4+ T cells that, along with other resistance factors, make them essentially unable to support a spreading infection." (PMID 25809491, 2015). "Together, these data suggested that the D/P vaccine-elicited, long-lived T cells rapidly expanded (CD8>CD4) with a type 1 effector phenotype in response to challenge infection, and were capable of controlling T. cruzi infection." (PMID 25951312, 2015). "We found that Il-22 gene transcription, as well as IL-22 protein levels were dramatically reduced in the colons of Tcr-β-/- mice indicating that CD4+ T cells are the primary source of IL-22 at this time point in the infection." (PMID 26285214, 2015). "Here, we show that repeated exposures of the skin to infective S. mansoni cercariae results in an early increase in IL-10 production by CD4+ T cells at the skin site of infection." (PMID 25974019, 2015). "CD4 downregulation has been thought to occur only in productive infection, but our data support the notion that CD4 downregulation can occur in infected resting cells with minimal viral replication." (PMID 26537682, 2015). "There were 13 cats in the study group with CD4+ T lymphocyte counts <200 cells μl−1 recorded at the final sampling, indicative of terminal infection (by analogy to HIV infection)." (PMID 25395594, 2015). "With impaired immunity especially in patients with CD4+ T cell counts < 200 cells/mm3, infections with opportunistic intestinal parasites result in diarrheal symptoms." (PMID 25658626, 2015). "For these studies, we utilized an in vitro model based on the infection of unstimulated primary CD4 T cells with wild-type HIV isolates." (PMID 26539983, 2015). "In fact, approximately 45% of animals immunized with the pcTPANS1 and depleted from CD8+ cells survived virus challenge, while all vaccinated animals depleted from CD4+ cells died after infection." (PMID 26650916, 2015). "At week 6 post-infection, mice receiving CD4+Foxp3- T cells + Treg showed the greatest numbers of cells producing IFN-γ, IL-17 and IL-4." (PMID 26512987, 2015). "Overall, untreated PBMCs and untreated HLACs from both lymphoid tissues displayed lower levels of productive infection than untreated CD4+ T cells isolated from each tissue." (PMID 26067822, 2015). "Here, we used NSG HuMice to interrogate the respective importance of CD8+ T cells vs. deletion of CD4+CCR5+ T cells in the control of viral replication during the acute phase of the infection." (PMID 26407077, 2015). "G-to-A hypermutation signatures in viral genomes after nine days of infection in chimpanzee primary CD4+ T cells are dependent on Vif." (PMID 26394054, 2015). "Among men and women in a generalized epidemic, the initiation of antiretroviral therapy (ART) at a CD4 cell count between 350–550 cells/μl was shown to prevent 96% of new infections as compared to treatment initiation at CD4 <250 cells/μl." (PMID 26554586, 2015). "ESAT-6 targeting to DEC205+ APCs prior to infection importantly reduces the onset time for specific-CD4+ and CD8+ T cell responses, correlating with cellular infiltrate, in vivo CTL killing assays and, ultimately, with reduced bacterial load in the lungs." (PMID 25915045, 2015). "CD25+Foxp3+CD4+ Tregs increased from 7 days post-infection until 28 days post-infection in the lungs for all Mtb strains." (PMID 26675186, 2015). "At low doses of infection both CD4+ and CD8+ T cells polarise into IFN-γ-secreting effector cells, resulting in the host being unable to expel the worms." (PMID 25942314, 2015). "As we previously showed, attachment to cells during spinoculation is highly CD4-driven, hence allowing a synchronized initiation of infection in our experimental design, starting from CD4-bound virions." (PMID 26158270, 2015).
infection (continued). "Our results on infections in primary chimpanzee CD4+ T cells show that there is a clear Vif-dependence of infection, where the SIVsmm Vif poorly supports viral replication in these cells." (PMID 26394054, 2015). "The analysis of the spleen from the IG infected animals, 26 six days post infection, showed approximately the same number of CD4+ cells observed in the control group." (PMID 26469517, 2015). "Moreover, when untreated, HIV infection may be considered in two stages according to the CD4 cell count threshold: below or above 350 cells/mm3 (i.e., "remote" vs. "recent" infection, respectively); this presumes an increased risk of death in individuals with ≤ 350 CD4 cells/mm3." (PMID 26091253, 2015). "We observed a similar small fraction of B cells and CD4+ T cells staining for Ki-67 in the adult and old mice between days 0 and 4 after infection." (PMID 26204259, 2015). "Other research groups found such inhibitory activity only when certain herpes viruses were already present and pre-established an infection in CD4+ T cells." (PMID 26132818, 2015). "The role of CD4 T cells in generation of an antibody response to the primary infection is also of potential importance." (PMID 25572799, 2015). "Similar effects as those of FV infection on PD-L1 expression were also found for the infection of human CD4+ T cells with HIV-1." (PMID 26484769, 2015). "To determine the kinetics of the CD4:CD8 ratio inversion over the course of infection, we compared absolute CD4+ and CD8+ T lymphocyte numbers from 17 cats from Group 2 that died during the study." (PMID 25595267, 2015). "Immunocompromised mice, which lack CD4+ T-cells, are able to control the infection by Δsgl1 and acquire immunity against the challenge by wild-type C. neoformans following vaccination with the Δsgl1 strain." (PMID 26322039, 2015). "HHV6 has also been shown to have immunomodulatory effects, including infection of CD4+ T cells and induction of Treg cells 36–38." (PMID 26029371, 2015). "We observed a decreased number of LFG KO activated CD8 and CD4 T cells throughout the infection and a marked decrease in LFG KO LCMV specific memory T cells." (PMID 26565411, 2015). "CD4+ DEC obtained from 1x mice on day 1 after infection exhibited very low levels of proliferation to parasite antigen, which was similar to those in DEC cultured without antigen (no-antigen controls)." (PMID 25974019, 2015). "Human immunodeficiency virus type 1 (HIV-1) depletes CD4+ T cells in blood, secondary lymphatic tissues, gut and lungs by mechanisms such as the cytopathic effects of infection, immune recognition and killing of infected cells." (PMID 25933119, 2015). "HIV, which is usually transmitted through unprotected sex with an infected individual, gradually destroys CD4 lymphocytes and other immune system cells, leaving HIV-positive individuals susceptible to other serious infections and to unusual cancers." (PMID 26348035, 2015). "Although the relative contributions of each type and response of CD4+ helper T cell during different stages of infection remain poorly understood, these cells are involved in maintaining protective or pathogenic conditions in response to Mtb infection." (PMID 26675186, 2015). "Instead our studies suggest a key cell-intrinsic migratory defect in naïve CD4+ T cells from old mice that occurs in vivo prior to antigen stimulation at very early times relative to infection." (PMID 26204259, 2015). "The establishment of such a prodigious in vivo infection provided a window of opportunity to directly examine the status of endogenous SAMHD1 in memory CD4+ T cells during the acute infection." (PMID 25996507, 2015). "Despite MDDC questionable ability to get productively infected with HIV, they play a major role during HIV-1 trans infection of CD4+ T cells as previously reviewed." (PMID 26733986, 2015). "In contrast, CD4+ T cells were the only lymphoid population to express more lacZ following infection." (PMID 26709698, 2015).
infection (continued). "These S100 family members have also been shown to be chemotactic to CD4+ lymphocytes, induce monocyte trafficking, and facilitate the recruitment of immune cells to the site of infection." (PMID 26407704, 2015). "As a positive control, resting CD4+ T cells were stimulated with αCD3/αCD28 activating beads in the presence of IL-2 for 72 h prior to infection, which led to significant expression of both CD69 and CD25 activation markers." (PMID 26067822, 2015). "This study investigated the characteristics of virus-specific CD4+ T cells after vaccination with a formalin-inactivated TBE vaccine in comparison to the response raised during natural infection." (PMID 26465323, 2015). "This suggests that IL-7 treatment and SAMHD1 knockdown lead to silent infection events in resting CD4+ T cells, and, thus, an underestimation of the latently infected cell population." (PMID 26067822, 2015). "In the second scenario (ART initiation according to Mexican guidelines at CD4+ count of 350cells/mm3), the time from infection to ART initiation was estimated at 2.8 years." (PMID 26302044, 2015). "We investigated double infection of unstimulated primary CD4+ T cells using reporter viruses carrying genes for different fluorescent proteins, EGFP and mCherry, combined with sophisticated modeling techniques based on Poisson distribution." (PMID 26559763, 2015). "An acute infection assay utilizing CD4+ cells from MHC-mismatched monkeys to avoid cytolytic responses was employed." (PMID 26551355, 2015). "Clonal amplification appears to be a distinct type of virus-host interaction where infection of a population of CD4+ T cells in a compartment is a low probability event and when it occurs there is transient rapid expansion of the viral population." (PMID 25811757, 2015). "Both the frequencies and absolute numbers of CD4+ T-cells decreased steadily throughout infection albeit we observed a tentative of restoration at day 14 post-infection." (PMID 26107380, 2015). "Increasing the CD4+ count at ART initiation to 350 cells/mm3 shortened the time since infection to 2.8 years." (PMID 26302044, 2015). "Mice receiving CD4+Foxp3- T cells showed significantly higher numbers of lymphocytes, macrophages and granulocytes in the lungs at weeks 2 and 6 post-infection as compared to mice receiving Treg cells alone or in combination with CD4+Foxp3- T cells." (PMID 26512987, 2015). "HIV-1 capture by both LPS-DCs and IFN-α-DCs and subsequent trans-infection of CD4+ T cells were similarly enhanced over that observed with immature DCs." (PMID 25760631, 2015). "As a first attempt to analyze the role of T cells in the control of FLUAVsw infection, we looked for expansion of CD4 and CD8β effector T cells via analysis of Ki-67 expression." (PMID 25971313, 2015). "RORγC mRNA levels at week 2 and 6 post-infection were higher in mice reconstituted with CD4+Foxp3- T cells + Treg cells, followed by mice given CD4+Foxp3- T cells and then by mice receiving Treg cells." (PMID 26512987, 2015). "Here we show that under conditions in which efficient CD4+ T lymphocyte infection required contact-dependent VS formation with infected MDM, Vpr promoted VS-mediated transmission of HIV-1." (PMID 26186441, 2015). "This impact of immunity on treatment scale-up requires further modeling and analysis particularly given the data showing that individuals treated during the acute phase of an infection develop functional CD4+ and CD8+ responses." (PMID 26295805, 2015). "These cytokines establish a chronic inflammation state and attract more CD4+ T cells to the inflamed sites, resulting in more infection and cell death." (PMID 26709961, 2015). "Following Lm‐2W1S infection, three subsets of CD4+ T cells can be defined: CXCR5−PD‐1−T‐bet+ effector cells (Teff) that give rise to Tem cells, CXCR5+PD‐1−Bcl‐6+ central memory precursors that give rise to Tcm cells and CXCR5+PD‐1+Bcl‐6+ Tfh cells." (PMID 25754933, 2015).
infection (continued). "By day 4 after infection, CD4+ T cells became the predominant source of IL-10 in both 1x and 4x infected pinnae." (PMID 25974019, 2015). "The authors used CD4 at diagnosis to estimate year of infection for each of the adults in their study population and taking into account the variable “Year of Migration”, assigned probable place of HIV acquisition." (PMID 26085030, 2015). "In a large-scale observational study involving 18,495 seroconverters, the interval from infection until the CD4 cell count reached <350 cells/μL was estimated to be 4.19 years." (PMID 26000028, 2015). "We observed a considerably enhanced CD25+ pSTAT5+ population from TGF-βRII KO early effector cells relative to the WT cells, suggestive of heightened IL-2 signaling in the TGF-βRII KO CD4 T cells in vivo during infection." (PMID 25569154, 2015). "The interaction between MMTV Env protein and Toll-like receptor 4 allows the infection of B cells, that present Sag (Super Antigen) to CD4+ T cells." (PMID 26214095, 2015). "Infection with P. falciparum in infancy also altered the immune cell profile, with infants infected before 3 months of age having a higher frequency of CD4+ T cells and a lower frequency of CD8+ T cells." (PMID 26580401, 2015). "In agreement with previous studies, double infection of CD4+ T cells occurred more frequently than expected." (PMID 26559763, 2015). "Human immunodeficiency virus (HIV-1), the leading infectious killer worldwide, dysregulates the immune system primarily through infection and depletion of CD4+ T cells." (PMID 26186441, 2015). "Following Mtb challenge of BCG vaccinated mice, Th17 induced chemokines, recruited CD4+ T cells to the site of infection, favored granuloma formation, and accelerated pathogen clearance." (PMID 26640327, 2015). "We have studied HIV expression in an in vitro model of latency that involves direct infection of primary resting CD4+ T cells in which viral spread is undetectable." (PMID 26537682, 2015). "The percentage of T-bet+ CD4+ T cells on day 3 post-infection was increased in the FeD mice, concurring with the increased percentage of CXCR3+ CD4+ T cells observed on this day." (PMID 25768944, 2015). "Although not statistically significant a similar trend of increased CD69 expression was noted on CD4+ T cells at day 14 and day 28 post-infection." (PMID 26322025, 2015). "A D368R mutation was introduced into these soluble Env competitors to prevent them from binding to cellular CD4 and thereby directly inhibiting infection." (PMID 26023780, 2015). "Template DNAs were extracted from CD4+ T cells isolated from macaque peripheral blood mononuclear cells (PBMCs) obtained at approximately 2 years post-infection." (PMID 26536034, 2015). "Untreated HLACs from the spleen resulted in an 11-fold decrease in productive infection as compared to untreated CD4+ T cells from the same tissue." (PMID 26067822, 2015). "Upon infection, the number of human CD4+ T cells in the periphery increased rapidly with the presence of abnormal T cells displaying lobulated nuclei resembling ATLL-specific “flower cells”." (PMID 26690200, 2015). "This transient upregulation of CD4 has also been reported after infection of γδ T cells with human herpesvirus." (PMID 26473478, 2015). "We measured the parasite numbers in CD98hcf/f-CD4 mice and CD98hc+/+-CD4 mice infected with Leishmania major 70 days after infection." (PMID 26444422, 2015). "Thirty-four individuals with a known primary infection, presenting with a CD4 count below 350 cells/μl or an ADE at diagnosis, were reclassified as NLPs." (PMID 26584954, 2015). "Consistent with previous reports, we observed that the serum IgE concentration reaches about 10-fold higher levels after secondary as compared to primary infection with N. brasiliensis, and this effect was dependent on the presence of CD4+ T cells." (PMID 26523376, 2015).
infection (continued). "Several studies have examined integration in latently infected cells by direct infection of resting and activated CD4+ T cells in vitro [53, 64•, 65, 66••]." (PMID 25573791, 2015). "LCMV clone 13 infection is ultimately controlled by cell-mediated and humoral immune responses by day 60–90 post-infection in CD4 T cell-sufficient mice." (PMID 25590581, 2015). "More importantly, we found in our longitudinal study that subjects who had higher CD4+ T-cell counts throughout the infection period and had slow disease progression had persistently higher B-cell counts." (PMID 26436092, 2015). "CD4 Th1 immunity is critical to sustain residual CD8 T-cell activity to control infection during persistent infection and is characterized in CD4 T cells by the secretion of IFN-γ, TNF-α, and IL-2." (PMID 26322025, 2015). "This raised the question if the IgG antibodies seen at 32 days post infection (dpi) in four out six animals of the IN group were also preceded by an increase of PCV2-specific cytokine-producing CD4+ T cells." (PMID 25888899, 2015). "In accordance with the kinetics observed for IL-21 mRNA expression, the percentage and total number of IL-21-producing CD4+ T cells in the spleen increased early after infection." (PMID 25763578, 2015). "Consistent with the increased activation phenotype of Ahr-/- CD4+ T cells during infection, these lymphocytes produced increased amounts of IFN-γ following stimulation with PMA/ionomycin." (PMID 26010337, 2015). "As Tfh have emerged as an important CD4 T cell subset that promotes late B cell responses to LCMV cl 13 infection, we examined the effects of GITR on Tfh." (PMID 25590581, 2015). "In SQ, MSM take an average 7.4 years since infection to initiate treatment with a median CD4+ count of 148 cells/mm3(25th-75th percentiles 52–266)." (PMID 26302044, 2015). "As expected, the confidence interval for Vδ2 cells was much greater than for r-CD4 cells due to the lower number of Vδ2 cells assayed and therefore the estimation of the frequency of infection is less accurate." (PMID 26473478, 2015). "This comprehensive study highlighted that CD4 Trm cells provide significantly more protection than circulating memory CD4 T cells to a challenge infection with Chlamydia trachomatis." (PMID 26441961, 2015). "Dans notre série, les mères au stade clinique 3 de l'OMS, celles présentant une infection opportuniste et celles ayant un nombre de CD4 <350/mm3 avaient statistiquement un risque élevé de transmettre le VIH chez leurs enfants." (PMID 26600917, 2015). "Cell sorting by flow cytometry suggested that ghrelin-treated IL-17A+ T cell number was significantly restored by Ad-S6K1 infection both in splenic total T cells and CD4+ T cells." (PMID 25658305, 2015). "The expression of IFNγR2 on splenic CD4+ T cells was reduced on day 7 post-infection in the FeD mice." (PMID 25768944, 2015). "Ectromelia virus (ECTV) infection of Fas- and FasL-deficient mice led to increased virus titers in lungs and decreased migration of IFN-γ expressing NK cells, CD4+ T cells, CD8+ T cells, and decreased IL-15 expression." (PMID 25873756, 2015). "Transfer of intact CD4 T cells from a prior infection confers protective pulmonary immunity to N. brasiliensis in naïve mice." (PMID 25629518, 2015). "It is nevertheless plausible to suppose that any infection-induced expansion of a population of CD4+ T cells in such infants will primarily comprise atypical, transitional cells that have not undergone full maturation." (PMID 26580401, 2015). "A striking difference became apparent when we examined the expression of CD43 in the intrahepatic CD4+ T cell population during infection, as our data indicated that the majority of the CD4+ T cells, like the CD8+ T cells, were CD43+." (PMID 25874567, 2015). "In animal #9, we observed a massive increase in the frequency of cytokine+CD4+ T cells at one week post secondary infection (i.e. five weeks after primary infection)." (PMID 25971313, 2015).